TNF (tumor necrosis factor)
Diseases named in the same sentence as TNF in open-access papers (continued):
Sharing a sentence is not in itself a finding about the gene and the disease.
diabetic nephropathy (continued). "As evidenced in diabetic nephropathy, the pro-inflammatory cytokine TNF-α suppresses COL4A1 synthesis through the IRE1α/XBP1 endoplasmic reticulum stress pathway." (PMID 40646747, 2025). "In this research, we investigated the role of vitamin D and basic inflammatory biomarkers, serum highly sensitive CRP (hs‐CRP) and TNF‐α, and their possible interactions in diabetic kidney disease in an Iranian population." (PMID 40804707, 2025). "During podocyte injury and diabetic nephropathy progression, Tim-3 activates Mφ and triggers its NF-κB/tumor necrosis factor (TNF)-α signaling pathway." (PMID 39781467, 2025). "A meta-analysis revealed that berberine significantly improved renal function indicators (such as BUN and SCR) and inflammatory factors (IL-6 and TNF-α) in animal models of diabetic nephropathy." (PMID 40661082, 2025). "CR-C1 is an ingredient in the Sishenwan formula, which has been shown in a study to modulate AGE-RAGE, IL-17, and TNF signaling pathways to produce therapeutic benefits on diabetic nephropathy." (PMID 40435181, 2025). "In particular, it can regulate inflammatory factors such as TNF - α, IL - 1, and IL - 6, thereby preventing the occurrence of diabetic nephropathy." (PMID 40296871, 2025). "(TC-PLA NPs) exerted renal protective effects in STZ-induced diabetic nephropathy rats by reducing the expression of inflammatory factors (TNF-α, IL-6) and stabilizing renal function indicators (Scr, BUN)." (PMID 41373787, 2025). "In diabetic nephropathy, increased SAA levels were directly associated with impaired HDL capacity to reduce the secretion of TNF-α from human peripheral blood mononuclear cells (PBMCs)." (PMID 39120243, 2024). "Piperine and its derivatives significantly alleviate the conditions of diabetic nephropathy by decreasing the signaling of TNF-α, NLRP3 inflammasome, NF-κB, and IL-1β in a diabetic rat model." (PMID 38200253, 2024). "The stimulation of IL6 and TNFα production elicited by FGF23 is abolished in diabetic nephropathy mouse models injected with the carboxy-tail peptide of FGF23, which prevents iFGF23 signaling." (PMID 38791495, 2024). "A murine study demonstrated that blocking TNF-α in diabetic nephropathy led to reductions in albuminuria, serum creatinine, histopathological changes, and macrophage infiltration into the kidneys." (PMID 37711613, 2023). "The production of Interleukin-1β (IL-1β) and Tumor Necrosis Factor-alpha (TNF-α) was significantly increased in the glomeruli of diabetic nephropathy (DN) mice." (PMID 37638046, 2023). "Another prospective trial demonstrated that TNF-α predicted clinical outcomes and the development of diabetic nephropathy." (PMID 37974082, 2023). "Inflammatory markers, such as tumor necrosis factor-α (TNF-α), have been found to be elevated in patients with diabetic nephropathy." (PMID 37791152, 2023). "In humans, higher levels of MCP-1, IL-6, and TNF-α were found in biopsies of patients with diabetic nephropathy or morbid obesity." (PMID 37629165, 2023). "Our research describes that inflammatory cytokines IL-6 and TNF-α levels in kidney tissue are significantly increased in streptozotocin-induced diabetic nephropathy rats, indicating that these rats have kidney damage." (PMID 35685736, 2022). "The mRNA expression of TNF-α, a potent cytokine, is believed to play a major role in diabetic nephropathy." (PMID 35706905, 2022). "The expression of miR-93-5p was shown to be decreased in diabetic nephropathy, again under the regulation of lncRNA, and its inhibition reduced fibrosis and inflammation with a reduction in TNF-α, IL-6, and IL-1β." (PMID 36499023, 2022). "In an animal model of diabetic nephropathy, T cells were found to release TNF-alpha and interferon to activate endothelial cells and macrophages to exacerbate the inflammatory response." (PMID 36385487, 2022).
diabetic nephropathy (continued). "Actually, TNF signaling pathways play important roles in the progression of atherosclerotic and kidney disease and in particular in the progression of diabetic nephropathy." (PMID 35205271, 2022). "In addtion, IHC staining also revealed that TNF-α, IL-1β and IL-6 signifificantly increased in diabetic nephropathy kidney, its secretion can be suppressed by treatment of A&P." (PMID 35057768, 2022). "Treatment with AuNPs also induced a significant decrease in the mRNA expression levels of TNF-α in the diabetic nephropathy model, which suppressed the inflammation." (PMID 36060470, 2022). "Current evidence supports the antioxidant and anti-inflammatory properties of RSV, but its relationship with some inflammatory mediators such as IL-6 and TNF-α in animals with diabetic nephropathy needs further elucidation." (PMID 35355720, 2022). "Previous studies have also shown that administration of exogenous antioxidants can inhibit diabetic nephropathy due to inhibition of oxidative stress, resulting in a decrease in the production of inflammatory cytokines such as IL-6 and TNF-α." (PMID 35685736, 2022). "It has been reported that SGLT2 inhibition attenuates inflammation, including levels of CRP, IL-6, and TNF-α, and the progression of diabetic nephropathy." (PMID 35676606, 2022). "Subsequently, we subjected mouse kidney paraffin sections to IHC and found that the TNF-α level in tubular cells in the diabetic nephropathy group was significantly increased." (PMID 35280997, 2022). "TNF-α inhibition with infliximab and FR167653 decreased urinary albumin excretion, suggesting the role of TNF-α in the pathogenesis of diabetic nephropathy, with TNF-α inhibition is a potential therapeutic strategy." (PMID 35328704, 2022). "Interleukin 1 (IL-1), IL-6, IL-18, and tumor necrosis factor (TNF) are considered the crucial inflammatory cytokines in diabetic nephropathy." (PMID 35295847, 2022). "Cilostazol possessed beneficial effects on diabetic nephropathy by means of regulating protein kinase C, TNF-α, TGF-β, and oxidative stress-relevant NF-κB activation." (PMID 36544522, 2022). "Studies have also revealed that the TNF pathway plays an essential part in the progression of diabetic nephropathy." (PMID 36534664, 2022). "Cytokines of inflammatory such as IL-6 and TNF-α play a pivotal role in kidney damage that can be used as indicators of diabetic nephropathy." (PMID 35685736, 2022). "Current evidence supports the antioxidant and anti-inflammatory properties of resveratrol, but its relationship with the levels of some inflammatory cytokines such as IL-6 and TNF-α in animals with diabetic nephropathy needs further elucidation." (PMID 35355720, 2022). "Research has shown the effect of inflammatory processes and cytokines, including interleukin-1, interleukin-6, interleukin-18, and tumor necrosis factor (TNF), on diabetic nephropathy development." (PMID 35787282, 2022). "The aim of this study was to evaluate the impact of N6-carboxymethyllysine (CML)on NF-κB gene expression and tumor necrosis factor (TNF)production in diabetic nephropathy." (PMID 35894381, 2022). "As TNF’s role in diabetic nephropathy has been established, other renal diseases were investigated as well." (PMID 33670423, 2021). "A study on mice has revealed that TNF-α blockade in diabetic nephropathy confers kidney protection visible by reduction of albuminuria, serum creatinine, histopathologic changes, and macrophage recruitment to kidneys." (PMID 33670423, 2021). "M1 macrophage accumulation has been observed in the kidneys in diabetic nephropathy patients, in addition to the renal presence and degranulation (with prostaglandins and cytokines, such as IL-4 and TNF-α) of mast cells that correlate with disease progression." (PMID 33478014, 2021).
diabetic nephropathy (continued). "Increased TNFα levels have been related to the development of diabetic nephropathy involving reactive oxygen species accumulation and related cytotoxicity in kidney cells), while TNFα inhibition ameliorated the glomerular and tubular injury in diabetic kidney." (PMID 34572059, 2021). "Caffeic acid also had anti-inflammatory effects in the model of diabetic nephropathy (DN) mice by reducing renal IL-6, IL-1β, TNF-α, and MCP-1 levels." (PMID 35052518, 2021). "Studies show that TNF-α levels are higher in diabetic patients compared to healthy people, with its levels rising with worsening diabetic nephropathy." (PMID 33670423, 2021). "In studies in patients with diabetic nephropathy, the administration of vitamin E caused a reduction in the serum concentration of MMP-2, MMP-9, and TNF-α, while zinc was shown to decrease the Cd-induced expression of MMP-1 in synoviocytes." (PMID 32927885, 2020). "Diabetic nephropathy has been associated with tissue inflammation, including increases in cytokine of TGF-β (CTGF) and tumor necrosis factor (TNF)α." (PMID 30813549, 2019). "Oral administration of strawberry leaf extract decreases the serum levels of TNF-α in a rat model of diabetic nephropathy." (PMID 30291211, 2018). "It was found that the TGF-β1 pathway, AMPK signaling pathway, insulin-related signaling pathway, lipid metabolism, and TNF-α pathway were the major pathways of treatment of GDC for diabetic nephropathy." (PMID 29853965, 2018). "Effector molecules of the innate immune system including C-reactive protein, interleukin-6, and tumor necrosis factor-α are increased in patients with diabetic kidney disease." (PMID 29910771, 2018). "In an in vivo study, Pal and colleagues demonstrated that mangiferin suppressed inflammatory lesion in diabetic nephropathy by reducing TNF-α and IL-6 levels along with reduced expression of IKK and subsequent inhibition of NF-κB pathway activation." (PMID 28181586, 2017). "Urinary TNF-α levels were also elevated in diabetic patients with increased urinary albumin excretion and there was a significant rise in urinary TNF-α excretion as diabetic nephropathy progressed." (PMID 26239462, 2015). "In this study, there was a significant increase in TNFα gene expression in the diabetic nephropathy group compared to the control group." (PMID 24606996, 2014). "It is known that among inflammatory cytokines, such as TNF-α and IL-6 are relevant to the development of diabetic nephropathy, with diverse actions potentially involved in the development of complications." (PMID 24886259, 2014). "PPS has also been shown to reduce TNFα-induced changes and to block the development of diabetic nephropathy in mice." (PMID 23691192, 2013). "Among them, TNF-α (tumor necrosis factor-α) is the main proinflammatory cytokine, which acts toward the progression of diabetic kidney disease through recruitment of macrophages and neutrophils into the kidney." (PMID 23737649, 2013). "A previous study also demonstrated that azelnidipine significantly decreased plasma levels of monocyte chemoattractant protein-1, IL-6, hsCRP, TNF-α, 8-epi-prostaglandin F2α, and 8-hydroxydeoxyguanosine in patients with diabetic nephropathy." (PMID 21906391, 2011). "The kidney macrophages can produce a variety of substances which can promote renal injury, such as nitric oxide, ROS, IFN-γ, and IL-1, and TNF-α resulted in renal injury in diabetic nephropathy." (PMID 21716679, 2011). "In this context, MRP8/14 was in our study positively associated with Interleukin-6 as marker for systemic inflammation and TNF-α as marker for metabolic driven inflammation in patients with diabetic nephropathy." (PMID 19232095, 2009). "Increased serum TNF-α downregulated nephrin expression in the glomeruli in diabetic nephropathy." (PMID 40421989, 2025).
diabetic nephropathy (continued). "The ethanol extract of LB can inhibit the activation of NF‐κB in the renal tissue of diabetic nephropathy rats and reduce the levels of serum TNF‐α and IL‐6, thereby reducing the renal pathological damage caused by inflammatory reactions and improving renal function." (PMID 41036511, 2025). "Similarly, Aldahr and El-Kader conducted a study in Saudi Arabia, which found that aerobic exercise significantly improved kidney function, reduced oxidative stress, and lowered inflammatory markers such as IL-6 and TNF-α in patients with diabetic nephropathy." (PMID 39569233, 2024). "As a result, there is a simultaneous increase in neutrophil count, accompanied by a decrease in tumor necrosis factor, KC, interleukin 6, and interleukin 1β,42–44 these factors exhibit a strong correlation with the onset and progression of diabetic nephropathy." (PMID 38095344, 2024). "Previous studies revealed that 6-shogaol ameliorated diabetic nephropathy in db/db mice partly through its anti-inflammatory action by decreasing the TNF-α, monocyte chemotactic protein-1 (MCP-1), and IL-6 levels in the circulation and kidneys while suppressing NF-κB expression." (PMID 36355111, 2022). "In addition, apigenin-solid lipid nanoparticles (SLNPs) to reduce renal mRNA expression levels of IL-6, TNF-α, and IL-1β in streptozotocin-induced diabetic nephropathy rats." (PMID 36422572, 2022). "In addition, tetrandrine can reduce the levels of inflammatory factors TNF-α and IL-6 and elevate IL-10 level in rats with diabetic nephropathy (DN)." (PMID 35722158, 2022). "The inflammatory factors tumor necrosis factor (TNF) and interleukin-1 (IL-1) may be involved in the development of diabetic nephropathy." (PMID 35242879, 2022). "Other works also demonstrated that the administration of TNF antagonists inhibits salt retention, renal hypertrophy, and albuminuria, suggesting that TNF inhibition may slow the progression of diabetic nephropathy." (PMID 35328704, 2022). "However, serum IL-6 and TNFα have been reported to be used as predictors of kidney disease progression in diabetic nephropathy." (PMID 35350980, 2022). "During diabetic nephropathy, infiltrating macrophages can polarize to a pro-inflammatory M1 phenotype and promote TNF-alpha expression, facilitating the inflammatory response of DN and leading to the destruction of the glomerular basement membrane and Bowman’s capsule." (PMID 36385487, 2022). "Besides chemokines, the over expression of several inflammatory cytokines, such as IL1β and TNFα, have been identified as biomarkers in diabetic kidney disease." (PMID 35782913, 2022). "Serum bilirubin levels are positively correlated with the levels of the antioxidative enzymes as superoxide dismutase, catalase, and glutathione peroxidase, while it is inversely correlated with C-reactive protein, TNF-α, interleukin (IL)-2, IL-6, and IL-10 release in diabetic kidney disease." (PMID 35327498, 2022). "In an exploratory analysis, we also studied interactions between IL-9, the albumin/creatinine ratio (ACR) and urinary cytokines linked to the progression of diabetic nephropathy: vascular endothelial growth factor (VEGF), interleukin-6 (IL-6) and tumor necrosis factor alpha (TNFα)." (PMID 35445345, 2022). "Ellagic acid was also reported to lower TNF-α and IL-1β levels in diabetic nephropathy and nephrotoxicity kidney injury mice, which might be mediated through NF-κB; therefore, ellagic acid could be a potent inhibitor of NF-κB activation." (PMID 35956292, 2022). "The pro-inflammatory cytokine TNFα is believed to be a key inducer and driver of inflammation and plays a central role in the network of pro-inflammatory cytokines contributing to the pathogenesis of diabetic kidney disease (DKD) progression." (PMID 34045516, 2021).
diabetic nephropathy (continued). "Studies have demonstrated that TNFα induction contributes to the development of multiple kidney diseases including cisplatin-induced renal damage, angiotensin II-induced glomerular damage, diabetic nephropathy, and obstruction-induced nephropathy." (PMID 33934104, 2021). "Also, inflammatory such as IL-6 and TNF-α are significantly correlated with HbA1c and diabetic nephropathy." (PMID 34917685, 2021). "Various biological effects mediated by TNF are relevant in diabetic nephropathy, including its direct cytotoxicity to renal cells, activation of cell pathways leading to apoptosis and necrosis, and induction of alterations in intraglomerular hemodynamics and reduction of glomerular filtration." (PMID 34411124, 2021). "Previous study had certificated some molecules could aggravate renal injury in diabetic nephropathy through the TNF-α pathway." (PMID 33714195, 2021). "Similarly, TNF is elevated in sera obtained from patients with diabetic kidney disease (DKD), as well as in an obese-diabetic mouse model that presents with kidney disease." (PMID 32508807, 2020). "Diabetic nephropathy is a low-grade inflammatory disease, yet this study revealed a strong connection with TNF-α, which is a well-known inflammatory cytokine associated with renal injury." (PMID 31218128, 2019). "It has been well known that cilostazol may possess beneficial effects on diabetic nephropathy by means of regulating protein kinase C, TNF-α, TGF-β, and oxidative stress relevant NF-κB activation." (PMID 31492153, 2019). "Inflammatory mechanisms, and in particular the tumor necrosis factor signaling cascade, contributing to progression of diabetic nephropathy might be counterbalanced by tacrolimus treatment." (PMID 28060893, 2017). "Therefore, inactivation of TNF-α by infliximab ameliorates diabetic nephropathy in streptozotocin-induced diabetic mice." (PMID 28078101, 2017). "Furthermore, PTX appears to have anti-inflammatory properties with demonstrated efficacy in decreasing serum and urinary TNF-alpha levels, in patients with diabetic nephropathy." (PMID 25922592, 2015). "Bermejo's study mentions that tumor necrosis factor-alpha (TNF-alpha) and interleukin-9 (IL-9) levels in the urine were higher in this group when compared to other kidney pathologies that were biopsied, such as acute tubular necrosis, diabetic nephropathy, or glomerulopathies." (PMID 38516472, 2024). "Notably, TNF-α is also found in serum and urine of patients affected by diabetic nephropathy." (PMID 36827456, 2023). "In addition, serum TNF-α levels are positively correlated with the course of diabetic nephropathy, and the possible mechanism is that TNF-α damages diabetic glomerular tissue by producing inflammatory response cytokines and increasing microvascular permeability." (PMID 35656465, 2022). "Additionally, Nrf2 could suppress inflammation by inhibiting TNF-α and NF-κB in diabetic nephropathy in cell lines, an animal model, or both." (PMID 35956292, 2022). "Furthermore, the abrogation of p38 MAPK signaling activation by GS-4997 in the kidneys in diabetic mice halted the progression of diabetic nephropathy and reduced the macrophage infiltration of these organs and the expression of genes that encode MCP-1 and TNF-α." (PMID 33478014, 2021). "Blockade of TNF-α secretion from high glucose activated macrophages and ROS-p38MAPK pathway might be effective therapeutic options to limit podocytes apoptosis and delay the progression of diabetic nephropathy." (PMID 28881810, 2017). "Therefore, the source of TNF-α that drives podocytes apoptosis in diabetic nephropathy remains unknown." (PMID 28881810, 2017). "Blockade of TNF-α secretion from high glucose activated macrophages and ROS-p38MAPK pathway might be effective therapeutic strategies for limiting podocytes apoptosis and the progression of diabetic nephropathy." (PMID 28881810, 2017).